CTLA4 (cytotoxic T-lymphocyte associated protein 4)
Diseases named in the same sentence as CTLA4 in open-access papers (continued):
Sharing a sentence is not in itself a finding about the gene and the disease.
tumor (continued). "Like PD-1, CTLA4 is an inhibitory receptor that prevents CD28-mediated co-stimulatory signals for immune response, while LAG3 contributes to a state of T cell dysfunction in the tumor microenvironment." (PMID 36354714, 2022). "Taken together, LAG-3 inhibitors may have a better therapeutic effect, further demonstrating a novel tumor immunotherapy target of LAG-3 beyond PD-1/PD-L1 and CTLA-4." (PMID 35958563, 2022). "Anti-CTLA-4 antibodies have been observed to reactivate as T lymphocyte agonists, regardless of the tumor T cells’ specificity." (PMID 36276117, 2022). "OX40L and CTLA4 were expressed at higher levels while 22 other proteins, including CD11c, were expressed at lower levels (FDR < 0.2 and p-value < 0.05) in TAS as compared to tumor epithelia." (PMID 36230846, 2022). "Last, but not least, immunological checkpoints, such as CTLA-4 and programmed cell death protein 1 (PD-1), are also involved in tumor progression." (PMID 36298592, 2022). "Interleukin-17 in pancreatic cancer recruits neutrophils, triggers neutrophil extracellular traps (NETs), and excludes cytotoxic CD8 T cells from the tumor, reducing the sensitivity of immune checkpoint blockade (PD-1, CTLA4)." (PMID 36466860, 2022). "Overexpression of co-inhibitory receptors (CTLA4, PDL1 and CD96) may promote the increase of depletion of T-cell, thus losing the anti-tumor function in the transmembrane protein 60 high expression group." (PMID 36744183, 2022). "ATOR-1015, a human CTLA-4 and OX40 bi-specific antibody, induced the activation of T cells and depletion of Treg cells, then reduced the tumor growth, and improved the survival in several syngeneic tumor models." (PMID 35585567, 2022). "Using poorly immunogenic mice with metastases (mammary carcinoma 4T1) as a model, the authors found that 9H10 (monoclonal antibody against CTLA-4) alone did not have an effect on the primary tumor and RT alone delayed tumor growth." (PMID 36140312, 2022). "To test whether INHBA is both necessary and sufficient to confer ICB resistance, we administered anti-PD1/anti-CTLA4 ICB therapy or IgG control antibodies to YUMM3.3-Ctrl and -βΑ tumor grafts." (PMID 35580932, 2022). "We found that bacteria-positive tumours showed reduced expression levels of CD4 and CD8, along with an increased expression of immunosuppressive molecules such as CTLA4 and ARG1, and an enrichment of CD66b+ myeloid cells, supporting previous bulk tissue analysis." (PMID 36385528, 2022). "In the tumor microenvironment, mTOR signaling regulates the activity of macrophages and T-cells through inflammatory factors like IL-10, TGF-beta, and membrane bound CTLA-4 and PD-1." (PMID 36304922, 2022). "Further, we did not notice any significant decrease in tumor progression in the anti-CTLA4 mAb-treated LS diet cohort, as compared with the NS plus anti-CTLA4 mAb cohort." (PMID 35741331, 2022). "Mice treated with PIC alone showed tumor growth that was comparable to that in control mice receiving sham treatments and PIC did not improve response when added to anti-CTLA-4, as compared to anti-CTLA-4 alone." (PMID 35999216, 2022). "Despite DCs having been loaded with tumor lysates or inhibited for inhibitory immune checkpoints in previous studies, there has been no investigation on the simultaneous silencing of CTLA-4 and tumor cell lysate loading on DCs." (PMID 35979362, 2022). "In the present report, we show that anti-CTLA-4 antibodies lacking Fc-mediated effector functions still induce robust anti-tumor activity in preclinical tumor models." (PMID 35237846, 2022). "The coligand of CTLA4 and CD28 is B7, which is expressed in APCs and tumor cells." (PMID 36042469, 2022).
tumor (continued). "As the response to anti CTLA-4 and PARPis, the increase in local IFNγ is competent to prohibit tumor growth, while this drug combination does not have similar roles to BRCA1-sufficient ovarian cancer." (PMID 35281059, 2022). "Indeed, one possible mechanism of anti-CTLA4 antibody therapy is the depletion of immunosuppressive TGF-β-producing Treg cells, thus facilitating the costimulation and expansion of tumor-specific CTL with improved clinical benefit." (PMID 35432319, 2022). "Hot tumor is characterized by high T cell and CTL infiltration in CT and IM, high immunoscore, and suppressed T cell function due to activated immune checkpoints such as PD-1, CTLA-4, TIM3, and LAG3." (PMID 36293435, 2022). "KDs increased tumor-reactive immune responses, including tumor infiltration of cytotoxic CD8+ T cells in malignant glioma mouse model and reduced the expression of T cell co-inhibitory receptors CTLA-4 and PD-1 and their ligands CD86 and PD-L1." (PMID 36432618, 2022). "In our study, tumours within the EIC overexpressed PD-1 and CTLA-4, but did not have a higher tumour mutation burden than those within the rest class." (PMID 35799269, 2022). "Tumor cells can escape the killing of tumor cells by T cells through downregulating MHC and upregulating the expression of inhibitory receptors such as PD-L1, CTLA-4, LAG-3, TIM-3 and TIGIT, and blocking the binding of these inhibitory receptors to ligands can restore T-cell anti-tumor activity." (PMID 36225938, 2022). "Treating the animals with CPI (anti-PD-1 and anti-CTLA-4 antibodies) alone showed just little effect on the growth of B16F10 tumors; meanwhile, the collagen-binding domain fused to IL-12 (CBD-IL-12) alone initially induced tumor regression." (PMID 36428682, 2022). "In order to understand the expression level of CTLA-4 on activated T-cells infiltrating tumor, an anti-CTLA-4 monoclonal antibody was radiolabeled with 64Cu ([64Cu]Cu-DOTA-anti-CTLA-4) and its binding specificity tested in vivo in CT26 tumor bearing mice." (PMID 35099641, 2022). "Furthermore, PBLs from patients with MPC showed a greater proportion of CD4+CD25+FOXP3+ Tregs, exhausted CD8+CTLA4+ T cells, CD8+CD122+ T cells, and CD8+CD45R+ T cells, which can be regarded as tumor-promoting cells, than in patients with BPC." (PMID 36333670, 2022). "However, PD-1 and also CTLA-4 are expressed not only on CTL but also on other T cell subtypes, other immune cell types, and even on tumor cells." (PMID 35013519, 2022). "Unlike CTLA-4, PD-1 primarily affects T cell activity in its effector phase in peripheral tissue and within the tumor." (PMID 35804917, 2022). "As opposed to CTLA-4, PD-1 is a negative regulator at the effector phase of T-cell activity at the tumour site." (PMID 35326677, 2022). "Furthermore, we found that CSF-1R was significantly correlated with tumor-related immunosuppressive molecules (including PDCD1, CTLA4, CD80, CD86, HAVCR2)." (PMID 35444953, 2022). "To gain insight into the mechanism of action of the observed synergistic effect, we performed immunohistochemical staining of CD8 and CD34 on paraffin embedded MCA205 tumor tissue sections from mice treated with anti-CTLA4 with or without propranolol." (PMID 35017664, 2022). "They showed that the radiotracer accumulation in the tumor was higher when compared with a conventional anti-CTLA-4 mAb, but not with anti-PD-1 mAb." (PMID 35625811, 2022). "Furthermore, immune checkpoint inhibitors (ICIs) like anti-CTLA-4 antibody or anti-TIGIT antibody combined with the blockade of CD25 potently resulted in the depletion of Tregs and enhanced anti-tumor responses in a mouse model." (PMID 36246629, 2022). "Preliminary data, however, showed that with the current setup, 50 to 100 μg BC CTLA-4 blockade did not result in tumor growth inhibition (data not shown)." (PMID 35890247, 2022). "Even when treated with combined RT and anti-CTLA-4, this TC11 tumor model was poorly responsive." (PMID 35999216, 2022).
tumor (continued). "While the inert Fc mCTLA-4 antibody had no anti-tumor activity, the anti-CTLA-4 mIgG2b Fc (which can mediate ADCC) showed a moderate decrease in tumor volume." (PMID 35379805, 2022). "We sought to apply iFRET to directly quantify PD-1/PD-L1 and CTLA-4/CD80 interactions in a cohort of patients in both their pre- and post-RFA-treated lung metastases, and iFRET results were correlated with the quantification of tumor-infiltrating lymphocytes." (PMID 36497220, 2022). "However, when RBMS1 is depleted, it destabilizes B4GALT1 transcript, resulting in the suppression of glycosylation and increased degradation of PD-L1, thus promoting anti-tumor T-cell immunity and sensitizing TNBC cells to anti-CTLA4 therapy." (PMID 35538152, 2022). "Assessment of the tumor immune infiltrate showed that subcutaneous tumors of mice with liver metastases had reduced CD8+ T cell expression of activation markers including ICOS, PD-1 and CTLA-4, as well as expression of intracellular IFNγ." (PMID 36466910, 2022). "Although anti-CTLA-4 is not prominent in immunotherapy as a monotherapy, it is being clinically tested in a variety of cancers as an effective means of enhancing anti-tumor response when applied with other therapies, such as chemotherapy and radiotherapy." (PMID 36120342, 2022). "Of interest, the combination of the NLRP3 inhibitor with anti-CTLA-4/anti-PD-1 did not demonstrate a significant synergistic effect in regard to tumor growth but only in the frequencies of MDSC subsets." (PMID 36032139, 2022). "Remarkably, even with a combination of anti-PD-1 and anti-CTLA-4 at a dose as high as 300 μg each, the scaffold-based treatment failed to effectively inhibit tumor growth." (PMID 35890247, 2022). "After mice were treated with anti-CTLA-4 mAb targeting CTLA-4, immunosuppressive TME was reduced and the infiltration of CD8+ T cells into the tumor was increased, which facilitated to improve antigen-specific CTL killing and anti-tumor effect in mice receiving anti-CTLA-4 mAb." (PMID 34875483, 2022). "In addition, synergistic cytotoxic T cell (CTL)-induced tumor cell death and the induction of the tumor suppressor PTEN were seen in a T cell-tumor co-culture treated with bispecific antibodies that target CHI3L1 and CTLA-4." (PMID 36618349, 2022). "In this study, Higashikawa and colleagues showed a high tracer uptake on T-cells and not on the tumor, and correlated it with the high expression of CTLA-4." (PMID 35099641, 2022). "From the perspective of tumor immunity, EMT is related to the dampening of CD4+ and CD8+ T cell responses by overexpression of TGF-β and IL-10, as well as the upregulation of immune checkpoints such as CTLA-4 and TIM-3 in lung carcinoma." (PMID 35647201, 2022). "CTLA-4 antibodies are no longer widely used, now limited to just a handful of tumours, due to their lower efficacy and more frequent side effects compared to PD-1 pathway inhibitors." (PMID 35228677, 2022). "Among them, CTLA4, TIGIT, TNFRSF4 and TNFRSF18 were highly expressed in tumor-infiltrating Tregs." (PMID 35562760, 2022). "Interestingly, the close association of the DTL gene and markers of Treg cells and T cell exhaustion, such as FOXP3, CCR8, STAT5B, PD-1, CTLA4, and LAG3, was found after adjusting the correlation values for tumor purity." (PMID 35392073, 2022). "Furthermore, there is evidence that enhanced inhibitory-receptor signals in T cells, such as CTLA-4 and PD-1, restrain glucose consumption and glycolytic capacity, leading to dampened mTOR activity and IFN-γ production, thereby allowing tumor progression." (PMID 35920986, 2022). "Interaction of immune checkpoint molecules like CTLA-4, LAG-3 or PD-1 with their ligands B7.1/B7.2 on antigen-presenting cells, fibrinogen-like protein-1 and Galectin-3 or PD-L1 on tumor cells, respectively, enhance immune escape of tumor cells." (PMID 36700232, 2022).
tumor (continued). "Anti-PD-1 or anti-PD-1/CTLA-4 treatment alone was not sufficient to achieve tumor regression in this model, possibly due to insufficient priming of T cells by myeloid CD206-DCs and/or the absence of dominant tumor antigens in this system." (PMID 35572601, 2022). "Actually, after T cell activation, CTLA-4 is expressed on the surface of activated T cells, and Treg cells also constitutively express CTLA-4, which would impair activation and expansion of anti-tumor T cells." (PMID 34875483, 2022). "Ligands of CTLA-4 are expressed on antigen-presenting cells in T cell priming but not commonly on tumor cells." (PMID 35013519, 2022). "Combined Therapy with vaccine and anti-CTLA-4 mAb enhanced CD8+ T cell infiltration of tumors by blocking CTLA-4, remodeling the immunosuppressive TME and normalizing tumor vasculature." (PMID 34875483, 2022). "Notably, anti-CTLA-4 therapy, when combined with a decrease in regulatory T cells, has been shown to enhance cytotoxic CD4+ T cell anti-tumor activity." (PMID 35831288, 2022). "The adaptive response is triggered by tumor-specific T cells via the production of IFN-γ and tumor-infiltrating lymphocytes (TILs), which can induce immune checkpoint molecules (such as CTLA-4) or immunosuppressive mediators (such as IDO1) to exert immunosuppressive effects." (PMID 35296094, 2022). "In the context of the TME, CTLA-4 expressing Tregs induced by metabolic alterations, may promote IDO expression in tumor-infiltrating DCs, reinforcing immune suppression." (PMID 36713558, 2022). "While the use of anti-CTLA-4 single did not affect the tumor, the combination of anti-CTLA-4 and RNActive vaccine considerably decelerated tumor expansion." (PMID 35620336, 2022). "•Combined therapy with MUC1 mRNA nanovaccine and anti-CTLA-4 mAb could reduce immunosuppressive TME, increase the infiltration of CD8+ T cells into tumor sites, and enhance anti-tumor cytotoxic T-lymphocyte activity when compared with each monotherapy." (PMID 34875483, 2022). "For the directly treated right flank tumors, tumor growth was again significantly decreased in the RT + anti-CTLA-4 and the PIC + RT + anti-CTLA-4 groups with the latter exhibiting significantly reduced tumor growth compared to RT + anti-CTLA-4." (PMID 35999216, 2022). "To comprehensively inspect the immune microenvironment of HCC TME, we firstly compared gene expression of immune inhibitory checkpoint molecules between tumor tissues and normal (peri-tumor) tissues, including CD274, CTLA4, HAVCR2, LAG3, PDCD1, PDCD1LG2, TIGIT, and SIGLEC15." (PMID 35444645, 2022). "Although anti-CTLA-4 therapy was initially used to augment the activity of tumor-infiltrating CD8+ T and CD4+ T cells, it has been suggested that this therapy exerts its effects through a cTreg-depleting effect in the tumor site." (PMID 35860556, 2022). "Furthermore, GILncSig was found to be associated with the upregulation of the expression of immune checkpoints, such as CD274, CTLA4, CD96, and TIM-3, which induced tumor immunotherapy resistance." (PMID 35571034, 2022). "Article B was excluded from the analysis probably because CTLA-4 did not receive much attention until the anti-tumor effects of anti-CTLA-4 antibodies were demonstrated." (PMID 34811710, 2022). "This is because GVAX in combination with PD-1 blockers increases CD8+TILs in PDAC and promotes the activation of CD8+T cells, resulting in the production of more tumor-specific IFN-γ in TME, which will help overcome Tregs, CTLA-4, and PD-1/PD-L1 immunosuppressive pathways." (PMID 35965504, 2022). "In the past decade, antitumor responses have achieved unprecedented rates of long-lasting tumor responses in patients with a variety of cancers, including HCC, which can be realized by antibodies blocking the CTLA-4 or PD-1 pathway, either alone or in combination." (PMID 36052169, 2022).
tumor (continued). "Synergistic cytotoxic T cell-induced tumor cell death and the heightened induction of the tumor suppressor PTEN were seen in co-cultures of T and tumor cells treated with bispecific antibodies that target both CHI3L1 and CTLA-4." (PMID 36618349, 2022). "Chemoradiotherapy-exposed TIMEs were highly enriched with newly infiltrated tumor-specific CD8+ T cells and tissue-resident memory T cells, moreover, the authors found that chemoradiotherapy combined with dual CTLA-4 and PD-1 blockade achieved optimal anti-tumor effects." (PMID 36532071, 2022). "There is evidence that blocking the PD-1 pathway alone or in combination with anti-CTLA-4 monoclonal antibody can produce antitumor effects in either NSCLC or SCLC, and combination therapy provides a larger tumor response; however, therapy-related toxicity also increases." (PMID 35159131, 2022). "Besides, the expression of cell exhaustion-related genes, including PDCD1, CTLA4, LAG3, and TIGIT, was upregulated in several tumors, indicating that UBE2S was intensely involved in tumor evasion via different mechanisms." (PMID 35578600, 2022). "Despite huge clinical progress in the last past year, a detailed understanding of the mechanisms supporting anti-CTLA-4 and anti-PD-1 induced tumor immune rejection is still lacking." (PMID 35339889, 2022). "To test whether PD-L1 is induced at the tissue level in response to anti–CTLA-4 therapy, we performed immunofluorescence staining of PD-L1 and CD3 in the liver and kidney of tumor-bearing mice treated with 9D9 alone or in combination with other therapies." (PMID 35239514, 2022). "Tumor microenvironment characterization showed the presence of PD-L1 and CTLA-4 in 10 and 2 tumors, respectively, and the absence of PD-1 in all specimens." (PMID 35628499, 2022). "Furthermore, there were significant differences in the immune-checkpoint expressions (e.g., CTLA-4, PD-1, and TIM-3) and HCC stage among the three immune patterns, which were significantly correlated with tumor progression." (PMID 35355983, 2022). "This study suggests that inhibition of immunosuppressive checkpoints, such as PD-1/PD-L1,CTLA4,TIM3, may improve the tumour microenvironment in PCNSL." (PMID 36061189, 2022). "CTLA-4 belongs to the family of CD28/B7 immunoglobulins (Ig) and, as an important checkpoint inhibitor, suppresses T-cell activation, leading to inhibition of tumour defence." (PMID 35406541, 2022). "Recent advances in the treatment of many solid tumours using checkpoint inhibitor (CPI) immunotherapy targeting the CTLA4 and PD1–1/PDL-1 axes held great promise for HGSOC, which is often characterised by increased tumour-infiltrating lymphocytes (TILs), a biomarker of response to CPIs." (PMID 35073851, 2022). "Interestingly, we also observed a parabolic expression in genes involved in immune exhaustion (e.g. TCF7, LAG3, CTLA4 and PDCD1), which is consistent with the peak of immune landscape remodelling at S2 tumours as shown by our data above." (PMID 35301339, 2022). "CTLA-4 is an inhibitory immune checkpoint receptor and a negative regulator of anti-tumor T-cell function." (PMID 35091676, 2022). "Anti-PD1 or anti-CTLA4 therapy was initiated 5 days after tumor grafting, fully controlled tumor growth, while parental Y3.3 tumors were controlled by anti-CTLA4, but not anti-PD1 treatment." (PMID 36230753, 2022). "In addition, clinical characteristics, including age, sex, histological grades, T stage, AJCC stage, tumour recurrence, sclerosis, HBsAg level, and expression of PDL1 and CTLA4, were also analysed between patients with high and low IHC scores." (PMID 36308411, 2022).